TNF (tumor necrosis factor)
Diseases named in the same sentence as TNF in open-access papers (continued):
Sharing a sentence is not in itself a finding about the gene and the disease.
Hypertension (continued). "Thus, the aim of this work was to determine the Th1/Th17 (IL-6, IL-2, TNF, IL-17 and IFN-γ) and Th2 (IL-4 and IL-10) serum profile in Venezuelan Chagasic patients stratified according amiodarone treatment, hypertension and arrhythmias." (PMID 28327099, 2017). "CRP level was a significant factor of the progression of hypertension in all models (P<0.001); apparently, TNF-α and IL-6 levels are not factors for progression of hypertension." (PMID 28837559, 2017). "Indeed, previous research has shown that TNF-α and IFN-γ are produced in excess in hypertensive animal models, contributing to the inflammatory infiltration of blood vessels and exacerbation of hypertension." (PMID 28910394, 2017). "Some evidence suggests that cytokine levels are increased in human hypertension, and serum levels of inflammatory cytokines (IFN-γ, IL-6, and TNF-α) have been positively correlated with BP in humans; thus, they can act as the important biomarkers of low-grade systemic inflammation." (PMID 28910394, 2017). "TNFα antagonism or genetic knockout of IL-627 has been shown to blunt ANG II-induced hypertension." (PMID 27092251, 2016). "The present study therefore investigated the effect of a single-pill combination of amlodipine and atorvastatin calcium on the circulating levels of ICAM-1 and TNF-α in patients with hypertension with or without prediabetes." (PMID 27610083, 2016). "Sirolimus reduced renal TORC1 activation but not TORC2, NF-κB DNA binding activity, CCL2 or TNFα expression, and abnormalities in cilia ultrastructure, hypertension and cardiac disease were also not improved." (PMID 27723777, 2016). "There are very limited studies conducted in Ghana to assess the correlation of IL-6 and TNF-α among T2DM patients with hypertension and non-diabetic participants in rural and urban settings." (PMID 26391589, 2015). "Hirota reported that casein hydrolysate containing Val-Pro-Pro and Ile-Pro-Pro supplementation in subjects with mild hypertension significantly reduced circulating TNF-α levels, although no alteration in circulating CRP level was found." (PMID 25671415, 2015). "In conclusion, subjects with H. pylori antibodies had a higher prevalence of IR (HOMA-IR >2), hypertension, and increased TNF-α than those without H pylori antibodies." (PMID 26020514, 2015). "Activation of TLR4 leads to downstream release of inflammatory modulators including TNF-α, IL-1β and MCP-1.Moreover, previous studies demonstrated that inflammation plays a crucial role in the pathogenesis of hypertension, and the development and progression of renalfibrosis." (PMID 26556241, 2015). "Presently, we tested the hypothesis that central TNF blockade prevents dysregulation of brain RAS components and attenuates Ang II-induced hypertension." (PMID 23691105, 2013). "We previously showed that angiotensin (Ang) II-induced hypertension is mediated by increased production of proinflammatory cytokines (PIC), including tumor necrosis factor (TNF), in brain cardiovascular regulatory centers such as the paraventricular nucleus (PVN)." (PMID 23691105, 2013). "Similarly, overweight and obese participants, as well as those with hypertension, had higher hs-CRP, IL-6 and TNF-α levels, compared to their respective normal weight and normotensive controls." (PMID 22769230, 2012). "Further biochemical analysis showed that with a hypertension phenotype, with and without DMT2, there was a positive association with adipokines such as leptin, leptin/adiponectin ratio, as well as TNF-α and ANG II." (PMID 23251471, 2012). "Furthermore, the expression of both tumor necrosis factor α (TNF-α) and IFN-γ secreted by T cells was increased in mice with Ang II-induced hypertension." (PMID 22567105, 2012).
Hypertension (continued). "We demonstrated that hypertension exacerbated Pb-induced neuroinflammation in the prefrontal cortex (PFC), hippocampus, and hypothalamus, as evidenced by increased levels of proinflammatory cytokines (IL-6 and TNF-α) and decreased levels of anti-inflammatory cytokines (CD206 and IL-10)." (PMID 39853035, 2025). "An animal study showed that increased plasma TNF-α concentrations possibly activated NADPH oxidase, resulting in the release of high superoxide levels from polymorphonuclear leukocytes and the possible development of hypertension through increased systemic oxidative stress and vascular tone." (PMID 38542788, 2024). "Notably, the main source of interferon (IFN)-γ and TNF are CTLs, and mice lacking any of these cytokines showed attenuated hypertension and renal injury in the presence of hypertensive stimuli, which aligns with the pathogenic role of CTLs." (PMID 38545112, 2024). "We found significant differences in DNA methylation of TNF-α at position 4 (19.46 ± 4.43% vs. 21.63 ± 4.36%) and total levels (55.34 ± 11.67% vs. 58.44 ± 10.01%) in the obese group between subjects with and without hypertension." (PMID 38542788, 2024). "It is known that long-term arterial hypertension increases the total number of mast cells, induces degranulation of the bladder, and increases the production of proinflammatory cytokines including IFN-γ, TNF-α, IL-1, and IL-17, which contribute to the pathogenesis of inflammation." (PMID 36865350, 2023). "In addition, we also conducted mediation analysis among TNF-a, LTL and rapid decline in renal function or the composite endpoint of kidney dysfunction in participants with hypertension, and no mediating effects were found by TNF-a." (PMID 37859695, 2023). "Whether or not TNFα driven prothrombotic mechanisms are operative in hypertensive disorders of pregnancies is debatable." (PMID 35455936, 2022). "However, an Italian real-world study demonstrated that abatacept is preferred as first-line biologic rather than anti-TNF in subject with specific co-morbidities, such as hypertension (39.13%) or pulmonary disorders (16.52%)." (PMID 34945038, 2021). "Furthermore, in a rat model of placental ischemia, ELP-p50i partially ameliorated placental ischemia-induced hypertension and reduced placental TNF-α levels with no signs of toxicity." (PMID 33445783, 2021). "Furthermore, after the adoptive transfer of T cells, Rag-1−/− mice challenged with ANGII significantly increased T cell production of IFN-γ and TNF-α and treatment with a TNF-α antagonist prevented hypertension induced by ANGII, indicating the role of inflammation in inducing hypertension." (PMID 33218096, 2020). "However, men with arterial hypertension (n = 16) had higher levels of TNFα than those without this co-morbidity (n = 26), (4.53 [3.57–5.05] vs. 3.8 [3.12–4.5] pg/ml, p = 0.03)." (PMID 28429138, 2017). "Prior to the present study, it was not clear whether TNFα specifically in the kidney played a significant role in the development of hypertension." (PMID 26916681, 2016). "Given the counterregulatory effects of the AT2-R, ACE2, and IL-10 on AT1-R, ACE1, and TNF-α overactivity, these results implicate that increased expression of AT2-R, ACE2, and IL-10 may play a protective role in the development of hypertension in intact females." (PMID 26783414, 2016). "Indeed, OSA patients with hypertension show reduced values of IL-10 accompanied by increased levels of TNF-α, IL-6, and CRP with respect to patients without high blood pressure." (PMID 25944984, 2015). "Previously, it has been reported that infusion of TNF-α to pregnant rodents to roughly equivalent levels seen in pre-eclamptic patients results in hypertension, though the degree of hypertension displayed is not equivalent to that seen in placental ischemia models." (PMID 26347650, 2015).
Hypertension (continued). "Immunofluorescence and western immunoblot analyses revealed that hypertension contributed to the activation of TLR4 and NF-κB, accompanied by significantly enhanced expression of proinflammatory mediators, such as tumor necrosis factor-α (TNF-α), interleukin-1β (IL-1β), and interleukin-18 (IL-18)." (PMID 24223475, 2013). "Notably, treatment with TNFα antibody could not rescue maternal hypertension, or the increase in mortality or decrease in body and brain weight in offspring from PE mothers." (PMID 37290815, 2023). "In the present study, TNF-α had no independent contribution to BRS in normotensive diabetic patients, depicting that inflammation may not be a major CV risk factor in T2D patients without hypertension." (PMID 36085061, 2022). "It is not clear, however, whether TNFα specifically in the kidney contributes to hypertension." (PMID 26916681, 2016). "In the current study, we investigate this hypothesis by examining central TNF inhibition via intracerebroventricular (ICV) etanercept infusion, a soluble TNF receptor fusion protein, on pro- and anti-hypertensive RAS components in the PVN in Ang II-induced hypertension." (PMID 23691105, 2013). "As inflammation is a key component in the pathogenesis of hypertension, the interaction between ANG II and TNF-α may play an important role in the modulation of hypertensive response; ANG II treatment induces the production of TNF-α in cultured cardiomyocytes and fibroblasts." (PMID 23251471, 2012). "TNFα and IL8 levels are significantly but moderately correlated (r2 = 0.64, p < 0.0001) with AMI patients without hypertension than AMI patients with hypertension (r2 = 0.53, p < 0.001)." (PMID 38216681, 2024). "Moreover, the results highlighted the idea that MVO could regulate the expression levels of targets, especially for TNF, CHRM1, ACE, IL10, PTGS2, REN, and F2, as well as neuroactive ligand–receptor interaction, the calcium signaling pathway, and PI3K-Akt signaling pathway to treat hypertension." (PMID 35308213, 2022). "In OSA patients with hypertension, OA did not affect circulating inflammatory marker levels (white blood cells count, CRP, IL-6, IL-10, and TNF-a)." (PMID 35866792, 2022). "Patients with hypertension but without LV hypertrophy showed reduced monocyte surface CD163 expression and plasma IL10 levels, but increased plasma TNF-α." (PMID 34368120, 2021). "IgG antibody titers were not correlated with TNF-α, NOX4, renin, and NO in hypertension subjects in any of the models (P>0.05)." (PMID 29752343, 2018). "Correlations among age, weight, BMI, IL-6, IL-8, TNF-α and TGF-β within group 3 (CAD patients without hypertension)." (PMID 28033321, 2016). "Correlations among age, weight, BMI, IL-6, IL-8, TNF-α and TGF-β within group 1 (patients with hypertension without CAD)." (PMID 28033321, 2016). "Subjects seropositive for H. pylori antibodies exhibited higher rates of hypertension, an increased incidence of a HOMA-IR index > 2.5 and a higher level of tumor necrosis factor-α than those without H. pylori antibodies." (PMID 26020514, 2015). "Multiple regression analysis revealed significant individual contribution of HOMA-IR, AI, IL6, hsCRP, TNFα, TBARS and hypertension status, but not BMI to the LF-HF ratio in the study group." (PMID 24265679, 2013). "Accumulated visceral adipose tissue produce and secrete a number of adipocytokines, such as leptin, tumor necrosis factor-α (TNF-α), interleukin-6 (IL-6), angiotensinogen, and non-esterified fatty acids (NEFA), which induce development of hypertension." (PMID 18416854, 2008). "However, increased stent numbers are not correlated with TNFα either in AMI patients with (r2 = 0.20, p = 0.006, CI 95% 0.0570–0.3227) or without hypertension (r2 = 0.038, p = 0.70, 95% CI -0.1603–0.2340)." (PMID 38216681, 2024).
Hypertension (continued). "Despite of the role of chronic inflammation in hypertension, novel anti-inflammatory marker serum PGRN levels and serum PGRN/TNF-α ratio had not been yet estimated in hypertensive patients and their association with systolic blood pressure (SBP) and diastolic blood pressure (DBP) is not explored." (PMID 32424472, 2020). "After adjusting for covariates such as age, gender, BMI, FBG, TNF-α, IL-6 and hs-CRP, GLM analyses showed that subjects with PWV and hypertension progression had higher baseline PWV, follow-up PWV and △PWV than those with no PWV and hypertension progression." (PMID 29433526, 2018). "It suggested that the effect of RAAS may not be mediated through modulation of hypertension as a crucial mechanism for development of CRI but it may operate by stimulation of chemokines like transforming growth factor β1 (TGFβ1), tumor necrosis factor α (TNFα) and interleukin 1 (IL1)." (PMID 17428349, 2007).
tuberculosis (715 papers, 2005 to 2026). A chronic, recurrent infection caused by the bacterium Mycobacterium tuberculosis. "Etanercept is suggested above other TNF-α inhibitors to minimize the risk of tuberculosis infection in individuals with latent tuberculosis infection reactivation or previously treated tuberculosis." (PMID 40371340, 2025). "Tumor necrosis factor inhibitors (TNFi) are known to increase the risk of tuberculosis (TB) reactivation, though cases involving Mycobacterium bovis are rarely reported." (PMID 39143434, 2025). "It is mainly preferred due to its lower risk of tuberculosis reactivation compared to anti-TNF agents." (PMID 40554357, 2025). "Of note, a negative interferon-gamma release assay, such as QuantiFERON, is often obtained before initiating anti-TNF agents due to the risk of tuberculosis reactivation." (PMID 40145913, 2025). "This contrasts with anti-TNF agents, which exhibit stronger associations with tuberculosis reactivation, highlighting pathway-specific infection risks." (PMID 40408459, 2025). "Patients who are serologically positive for T. gondii should be counseled on the risk that anti-TNF-α therapy can pose to their health, similar to how patients with tuberculosis are advised." (PMID 39959486, 2025). "By blocking TNF signaling, these therapies can dampen autoimmune activity but also increase the risk of serious infections, such as tuberculosis and pneumonia, due to impaired immune activation." (PMID 40299450, 2025). "Active tuberculosis is also associated with a decrease in polyfunctional and IL-2+ T cells and an increase in TNF-α+ CD4+ and CD8+ memory T cells." (PMID 39065554, 2024). "It must be kept in mind that anti-TNF agents do increase the risk of reactivation of tuberculosis, as well as pneumonia, and, as such, these conditions need to be ruled out and vaccinated against, respectively, before initiating these therapies." (PMID 39336887, 2024). "The increased risk of tuberculosis associated with TNF-a inhibitors is well documented, and it seems that many health care professionals extrapolate that risk to other biologic classes." (PMID 39356910, 2024). "The polymorphisms of IL6 and TNFα are closely linked to the development of tuberculosis, and TNFα serves as a protective factor against pulmonary tuberculosis." (PMID 39015338, 2024). "TNF-inhibitors, however, do have risk of serious but rare side effects, including invasive fungal infections and tuberculosis, so they must be used with caution." (PMID 38952592, 2024). "Many studies have reported that the induction of TNF-α after tuberculosis is associated with clinical deterioration and severe tissue injury." (PMID 39046230, 2024). "A nationwide population-based retrospective cohort analysis suggested that the use of anti-TNFα drugs is associated with an approximately 4 to 8-fold increased risk of active tuberculosis." (PMID 39204132, 2024). "Excessive TNF-α can cause immune-mediated tissue damage and inflammatory reactions, exacerbating the severity of tuberculosis and resulting in a reduced efficacy of PD-1 inhibitors." (PMID 39101140, 2024). "High levels of TNF-α can lead to tissue damage and inflammation, contributing to the pathology associated with tuberculosis, including the formation of caseous necrosis and lung damage." (PMID 38892443, 2024). "Many trials included in published meta-analyses have demonstrated that TNF-α inhibitors significantly increase the risk of tuberculosis in patients with rheumatic diseases (RA, AS, PsA)." (PMID 39070789, 2024). "There is, however, a paucity of meaningful data about the risk of active tuberculosis associated with biologics other than TNF-a inhibitors." (PMID 39356910, 2024). "The increased risk of active tuberculosis associated with TNF-a inhibitors has been well documented." (PMID 39356910, 2024).